TFEB (transcription factor EB)
Diseases named in the same sentence as TFEB in open-access papers (continued):
Sharing a sentence is not in itself a finding about the gene and the disease.
colitis (7 papers, 2017 to 2025). Inflammation of the colon. "The genes involved in autophagy/selective autophagy, including ATG16L1, IRGM, LRRK2, ATG7, p62, optineurin (OPTN) and transcription factor EB (TFEB) in colitis and in maintaining intestinal homeostasis, are noted." (PMID 36835075, 2023). "A recent study showed that mice with a conditional deletion of TFEB in the intestinal epithelium (TFEBΔIEC) had a defect in Paneth cell granules, lower expression levels of lipoprotein ApoA1 and exaggerated colitis upon DSS injury." (PMID 30669622, 2019). "Elucidation of the involvement of TFEB and other transcription factors in colitis will improve our understanding of the mechanism of autophagic regulation in the complicated pathogenesis of IBD." (PMID 30669622, 2019). "Hence, the TFEB-mediated anti-bacterial responses should primarily occur in the epithelium, suggesting an accurate site for further reaches of TFEB in colitis or other colonic diseases." (PMID 38711975, 2024). "It has been reported that TFEB may regulate the inflammatory response by regulating the autophagy-lysosome pathway and that specific knockout of TFEB in IECs aggravates dextran sulfate sodium (DSS)-induced colitis." (PMID 37441529, 2023). "More recently, it was shown that autophagy-related genes (ATGs), such as optineurin (OPTN), transcription factor EB (TFEB) and leucine-rich repeat kinase (LRRK), are associated with increased susceptibility to colitis, suggesting that these genes are important in colonic immune homeostasis." (PMID 30669622, 2019). "Thus, we document a novel role for TFEB in the expression of APOA1, a known protective factor against epithelial injury and colitis in rodents and humans." (PMID 29066772, 2017).
colon cancer (7 papers, 2019 to 2025). "Similar results were obtained in HT29 colon cancer cells, where glucose depletion downregulated TFEB but upregulated TFE3." (PMID 41275493, 2025). "Consistent with their reported activation in various cancer types, including colon cancer, we detected basal amounts of TFEB and TFE3 in nuclear fractions of control RKO cells by Western blotting analysis." (PMID 35354596, 2022). "To further validate the role of TFEB in cancer progression, we examined nuclear TFEB levels in SW620 (colon cancer cell line) cells and found that they were much higher than in CCD-18Co (normal colon cell line) cells." (PMID 33753903, 2021). "TFEB regulates autophagy in colon cancer cells by promoting Beclin1 expression, resulting in tumor cell metastasis." (PMID 32920551, 2020). "Notably, BRAFV600E-positive HT29 colon cancer cells also exhibited TFEB nuclear translocation upon PLX4720 treatment, suggesting a BRAFV600E-specific event." (PMID 30979895, 2019). "Data obtained from one study revealed that curcumin triggers autophagy in human colon cancer HCT116 cells by activation of lysosomal function via suppression of the AKT-MTOR signaling pathway and induces TFEB transcriptional activity by direct binding to TFEB." (PMID 36497321, 2022). "In contrast, tea polysaccharides repressed the proliferation of colon cancer line HCT116 cells by targeting lysosomes to induce cytotoxic autophagy, which might be achieved through mTOR- transcription factor EB (TFEB) signaling." (PMID 36496738, 2022).
gastric cancer (7 papers, 2021 to 2025). A primary or metastatic malignant neoplasm involving the stomach. "Furthermore, a recent study revealed that heparanase enhances gastric cancer progression independently of its enzymatic activity by triggering the transcription factor EB (TFEB)-driven autophagy, in addition to the associated cell proliferation." (PMID 36293542, 2022). "The confirmation for role of Wnt in gastric cancer metastasis is that function of TFEB in enhancing invasion of gastric cancer and EMT induction is essential based on stimulation of Wnt." (PMID 38334836, 2024). "Taken together, these results indicate that increased expression of HPA and TFEB in gastric cancer is correlated with advanced tumor stage and poor prognosis." (PMID 35970822, 2022). "We provide evidence here that active HPA and inactive HPA mutant proteins enhance gastric cancer cell growth, possibly attributed to TFEB-mediated autophagy." (PMID 35970822, 2022). "Immunohistochemistry was applied to detect HPA and TFEB in human specimens derived from fifteen paired patients with gastric cancer." (PMID 35970822, 2022). "Moreover, the elevation of HPA gene expression and upregulation of TFEB levels have been associated with advanced clinical stage and poor prognosis of gastric cancer, providing strong clinical support for a connection between TFEB and HPA." (PMID 35970822, 2022). "In contrast, in gastric cancer, TFEB promoted EMT by Wnt/β-catenin signaling activation." (PMID 36057632, 2022). "The dephosphorylated TFEB is subsequently translocated into the nucleus and activates the expression of autophagy and lysosomal genes which promote the autophagic process and thereby aggravate the growth of gastric cancer cells." (PMID 35970822, 2022). "Notably, HPA and TFEB were significantly elevated in gastric carcinomas compared with the adjacent gastric tissue." (PMID 35970822, 2022). "In addition, a study illuminates that the Wnt/β-catenin signaling pathway promotes the metastasis and EMT-related markers expressions via interacting with transcription factor EB (TFEB) in gastric cancer cells." (PMID 35355804, 2021). "Moreover, nonenzymatic HPA triggers TFEB-driven autophagy and the associated gastric cancer (GC) cell proliferation." (PMID 35970822, 2022). "However, our results are mainly derived from gastric cancer cell lines, and it is necessary to repeatedly verify the regulatory relationship between HPA and TFEB in animal in vivo experiments." (PMID 35970822, 2022).
ischemic heart disease (7 papers, 2021 to 2025). "Increased m6A methylation of TFEB mRNA and decreased m6A expression level of TFEB mRNA are caused by upregulation of METTL3 and downregulation of ALKBH5 in ischemic heart disease, which together prevent the maturation of autophagy." (PMID 38112620, 2023). "Methyltransferase like 3 (METTL3) reverses the transcriptional activity of TFEB by binding to the 3’-UTR end of TFEB and concomitantly methylating two m6A residues, thus playing a protective role in ischemic heart disease." (PMID 33679452, 2021). "For ischemic heart disease, METTL3 decreases the stability of transcription factor EB (TFEB) mRNA by increasing its m6A modification." (PMID 41446042, 2025). "The expression of METTL3 is known to increase in mouse models of ischemic heart disease and inhibits autophagy by down-regulating TFEB; but ALKBH5 can make the opposite effect by up-regulating TFEB." (PMID 35141221, 2022).
liver cancer (7 papers, 2016 to 2025). An epithelial or non-epithelial malignant neoplasm that arises from the liver. "Importantly, in the clinical data, low expression of TFEB was statistically associated with the incidence of liver cancer, indicating that TFEB may prevent liver cancer from metastasis." (PMID 33803301, 2021). "To understand the function of TFEB in liver cancer, we retrieved expression levels of TFEB and lysosome components in TCGA database and the Kaplan–Meier (KM) plotter." (PMID 33803301, 2021). "Our results suggest that TFEB-mediated upregulation of Sox9 expression plays a role in liver cancer development by inducing progenitor cell proliferation." (PMID 32424153, 2020). "We found that TFEB and the key components of lysosome were downregulated in liver cancer." (PMID 33803301, 2021). "Interestingly, compared with well-differentiated liver cancer patients, the nuclear expression of TFEB in patients with moderately and poorly differentiated cancer was upregulated more significantly (p < 0.01)." (PMID 31799198, 2019). "Interestingly, compared with well-differentiated liver cancer patients, the nuclear expression of TFEB in patients with moderately and poorly differentiated tumors was upregulated significantly." (PMID 31799198, 2019). "Interestingly, all analyzed autophagy markers were stable and/or up-regulated in liver cancer cells together with their attributed transcription factor, TFEB, as has been described previously." (PMID 27058414, 2016). "However, a role of TFEB in cell fate determination and liver cancer has not been investigated so far." (PMID 32424153, 2020). "Notably, depletion of TFE3, but not TFEB, in the liver of FlcnLiKO mice fully rescues the cancer phenotype and normalized mTORC1 signaling, highlighting TFE3 as the primary driver of liver cancer and mTORC1 hyperactivity in the absence of FLCN." (PMID 40189703, 2025).
renal fibrosis (7 papers, 2022 to 2024). A final common manifestation of a wide variety of chronic kidney diseases characterized by glomerulosclerosis and tubulointerstitial fibrosis. "Taken together, these results confirmed that DNMT3a-mediated TFEB promoter was hypermethylated, and demethylated by 5-Aza could recover fibrotic TFEB loss and alleviate renal fibrosis pathogenesis." (PMID 38481802, 2024). "Taken together, our findings supported the view that inhibitory effects of TFEB on UUO-induced renal fibrosis." (PMID 38481802, 2024). "In the present study, we identify steps in autophagy flux in the TFEB protective pathway compromised by UUO-induced renal fibrosis." (PMID 38481802, 2024). "In a recent study aimed at examining the role of TFEB in renal fibrosis reported that TFEB expression increased in renal tubules in adenine-induced renal injury mice." (PMID 38481802, 2024). "To gain insight into the pivotal role of TFEB in renal fibrosis pathogenesis, we first conducted a UUO mouse model." (PMID 38481802, 2024). "To more profoundly determine the effect of TFEB in renal fibrosis, we surprisingly found the TFEB declined to less basal levels at d 14 after UUO." (PMID 38481802, 2024). "The role of TFEB-mediated autophagy in renal fibrosis has been extensively studied, however, there are currently no reports on the role of TFEB-mediated lysosome biogenesis in renal fibrosis." (PMID 36225562, 2022). "The increased transcriptional activity of TFEB promotes not only renal cyst formation and renal fibrosis but also clear cell renal cancer at about 5 months of age, associated with β-catenin hyperactivation." (PMID 35468900, 2022). "We performed immunohistochemical staining and Western blot analysis to investigate the regulatory effects of TFEB transcription factors on UUO-induced renal fibrosis." (PMID 35897713, 2022). "In our study, TFEB down-regulation resulted in decreased autophagy and a subsequent decrease in renal fibrosis." (PMID 35897713, 2022). "Therefore, we not only investigated the role of TFEB in renal fibrosis from the overall expression level of TFEB, but also indicated the level of nuclear alterations in TFEB." (PMID 38481802, 2024). "Here, we found that TFEB was downregulated in unilateral ureteral obstruction (UUO)-induced human and mouse fibrotic kidneys, and kidney-specific TFEB overexpression using recombinant AAV serotype 9 (rAAV9)-TFEB in UUO mice alleviated renal fibrosis pathogenesis." (PMID 38481802, 2024). "In this study, we examined the preventive effects of TFEB suppression on renal fibrosis." (PMID 35897713, 2022). "We injected synthesized TFEB decoy oligonucleotides (ODNs) into the tail veins of unilateral ureteral obstruction (UUO) mice to explore the regulation of autophagy in UUO-induced renal fibrosis." (PMID 35897713, 2022). "However, the pathophysiological roles of TFEB in renal fibrosis and fine-tuned mechanisms by which TFEB regulates fibrosis remain largely unknown." (PMID 38481802, 2024). "Importantly, recent studies suggested that DNA methylation can lead to TFEB expression silencing 70, 71, thus suggesting that it may play a crucial role in determining autophagy and renal fibrosis." (PMID 38481802, 2024). "In addition, we also demonstrated that the overexpression of TFEB in kidney or TFEB promoter demethylation with 5A-za could effectively alleviate renal fibrosis pathogenesis." (PMID 38481802, 2024). "Thus, we also investigated whether TFEB overexpression could alleviate UUO-induced renal fibrosis." (PMID 38481802, 2024). "In our study, we suppressed the function of TFEB using synthetic decoy ODN to evaluate autophagic activity in the process of renal injury, which prevented renal fibrosis." (PMID 35897713, 2022). "In this study, the expression of TFEB transcription factors was suppressed using synthetic TFEB decoy ODNs injected into the tail vein of UUO mice, and the inhibition of autophagy in UUO-induced renal fibrosis was confirmed." (PMID 35897713, 2022).
renal fibrosis (continued). "Transcription factor EB (TFEB) is a major regulator of autophagy, and related experiments have shown that TFEB-mediated activation of autophagy may give rise to autophagic cell death and inflammation in renal tubular epithelial cells, resulting in adenine-induced renal fibrosis in CKD." (PMID 36105212, 2022). "Moreover, there is no available data regarding the direct regulatory role of TFEB on ATP6V0C expression and its specific mechanisms in the context of renal fibrosis." (PMID 38481802, 2024).
emphysema (6 papers, 2017 to 2023). "Briefly, these preliminary studies revealed that CS exposure induces localization of TFEB to aggresome bodies, which was associated with a decrease in lung function and increased severity of emphysema in COPD subjects." (PMID 29445254, 2017). "This further supports that CS impairs TFEB-mediated autophagy as a mechanism for the phagocytic defect in COPD-emphysema subjects, as well as fisetin's therapeutic potential to restore phagocytosis through TFEB induction." (PMID 29445254, 2017). "Interestingly, BEAS-2B cells and C57BL/6 mice exposed to either cigarette smoke extract (CSE) or a sub-chronic CS treatment showed defective autophagy in COPD-emphysema through the induction of the perinuclear localization of TFEB to aggresome bodies." (PMID 36009490, 2022). "TFEB-dependent autophagy induces the progression of emphysema." (PMID 35965629, 2022). "In a cellular model of chronic obstructive pulmonary disease (COPD) emphysema, β-galactosidase activity dropped when cells were treated with gemfibrozil to stimulate TFEB activity, suggesting that TFEB activation could prevent senescence induction." (PMID 36231114, 2022). "Emerging data suggest that induced autophagy impairment via Regulator Transcription factor-EB (TFEB) regulates the action of cigarette smoke, playing a central role in the progression of COPD emphysema." (PMID 37627282, 2023). "Treatment with Gemfibrozil, a potent TFEB-inducing autophagic drug, protected from CS-induced TFEB/autophagy-impairment and COPD-emphysema pathogenesis." (PMID 36009490, 2022). "In addition to TFEB, other mechanistic mediators of autophagy have been shown to participate in the sequential dysfunction or impairment of autophagy processes, contributing as a key mediator of COPD-emphysema pathogenesis." (PMID 32847034, 2020). "Additionally, TFEB-mediated autophagy has also been shown to control CS-induced cellular senescence, and bacterial phagocytic clearance, thus highlighting its protective role in CS-induced COPD-emphysema." (PMID 32847034, 2020). "We first focused on evaluating the role of transcription factor EB (TFEB), the master autophagy regulator that induces the transcription of various autophagy/lysosomal biogenesis genes based on our recent data suggesting its critical role in COPD-emphysema pathogenesis." (PMID 29445254, 2017).
endometrial cancer (6 papers, 2020 to 2025). Primary or metastatic malignant neoplasm involving the endometrium (mucous membrane that lines the endometrial cavity). "The estrogen-related receptor α (ERRα) drives lipid metabolism, together with PGC1α/PPAR; nevertheless, recent evidence shows that ERRα is a direct target of TFEB, and both are overexpressed in patients with endometrial cancer." (PMID 36231114, 2022). "The influx of calcium levels affects the calcium homeostasis and functions of mitochondria and lysosomes, ultimately regulating autophagy pathways by TFEB involved in the occurrence and progression of endometrial cancer." (PMID 35223931, 2022). "In summary, we found that the TFEB-ERRα signaling pathway regulates the invasion and metastasis of endometrial cancer cells through the EMT pathway and cell membrane fluidity." (PMID 35045880, 2022). "Overexpression of ERRα led to enhanced PGC-1α expression and increased activity of TFEB, promoting epithelial-mesenchymal-transition in endometrial cancer cells." (PMID 32920551, 2020). "Our data aim to demonstrate that whether PGC-1α and ERRα are involved in the regulation of EMT via TFEB, and affect invasion and migration of endometrial cancer." (PMID 32920551, 2020). "Therefore, we next examined whether TFEB activity was affected by overexpression of ERRα in endometrial cancer cells." (PMID 32920551, 2020). "TFEB promotes EC migration via EMT signaling, regulates wound healing via TFEB-ERR in EK and ECC-1 cells, increases membrane fluidity, and promotes endometrial cancer cell invasion in TFEB-ERR axis-induced lipid reprogramming." (PMID 36072980, 2022). "In sum, estrogen-mediated extracellular calcium influx may be the main regulatory factor related to autophagy regulated by TFEB and plays a vital role in linking the nongenomic and genomic effects in endometrial cancer." (PMID 35223931, 2022).
Glucose intolerance (6 papers, 2019 to 2025). Glucose intolerance (GI) can be defined as dysglycemia that comprises both prediabetes and diabetes. "Here the authors report that in stressed β-cells, lysosomal Ca2+ release promotes mitophagy via activation of the transcription factor EB (TFEB) and loss of β-cell TFEB aggravates glucose intolerance during high-fat diet." (PMID 35288580, 2022). "TFEB has been found to be associated with Tac-induced β cell dysfunction and glucose intolerance." (PMID 39913188, 2025). "The importance of mitophagy in β-cell function was also demonstrated in mice that developed β-cell dysfunction and glucose intolerance after treatment with a calcineurin inhibitor that hampered TFEB activation and mitophagy." (PMID 37653033, 2023).
hepatocellular carcinoma (6 papers, 2013 to 2025). A malignant tumor that arises from hepatocytes. "In summary, TFEB hepatic gene transfer decreased detrimental activation of liver apoptosis and fibrosis which underlines the pathogenesis of neonatal hepatitis, cirrhosis and hepatocellular carcinoma in AAT deficiency." (PMID 23381957, 2013). "In this study, we observed that lysosomal components and its transcription factor EB (TFEB) were downregulated in hepatocellular carcinoma (HCC) patients." (PMID 33803301, 2021).